MCAT (malonyl-CoA-acyl carrier protein transacylase)
Description:
Catalyzes the transfer of a malonyl moiety from malonyl-CoA to the free thiol group of the phosphopantetheine arm of the mitochondrial ACP protein (NDUFAB1). This suggests the existence of the biosynthesis of fatty acids in mitochondria. Also acts as a mitochondrial small ribosomal subunit (mt-SSU) assembly factor.
Synonyms: MCT; MT; fabD; FASN2C; NET62; MCT1; OPA15
Tractability: Small molecule: a structure with a bound ligand is known. PROTAC: ubiquitination databases record sites on it; its protein half-life has been measured.
Gene: Protein-coding gene on chromosome 22 (43,132,209 to 43,143,398, reverse strand). Ensembl gene ENSG00000100294.
Subcellular location: Mitochondrion
Subcellular location (Human Protein Atlas): Mitochondria
Pathways (Reactome):
Metabolism: Mitochondrial Fatty Acid Beta-Oxidation
Gene Ontology:
Molecular function: [acyl-carrier-protein] S-malonyltransferase activity; RNA binding; RNA folding chaperone; transferase activity
Biological process: fatty acid biosynthetic process; mitochondrial small ribosomal subunit assembly; fatty acid beta-oxidation; monocarboxylic acid metabolic process; RNA folding
Cellular component: mitochondrion; mitochondrial matrix
Genetic constraint (gnomAD): Loss-of-function variants: 22 observed, 19.97 expected, observed/expected ratio (o/e) 1.1, 90% interval 0.79 to 1.57. The upper end of that interval is the gene's LOEUF score, 1.57, which puts it in group 6 of 6, group 1 being the genes least tolerant of losing a copy. Missense variants: 534 observed, 490.48 expected, observed/expected ratio (o/e) 1.09, 90% interval 1.01 to 1.17. Synonymous variants: 240 observed, 210.85 expected, observed/expected ratio (o/e) 1.14, 90% interval 1.02 to 1.27.
Gene-disease validity (ClinGen):
ClinGen rates the evidence that MCAT causes each of these diseases.
optic atrophy 15 (autosomal recessive): Limited.
Homologues: Orthologues: chimpanzee MCAT (99% identical), macaque MCAT (94% identical), dog MCAT (79% identical), pig MCAT (79% identical), guinea pig MCAT (77% identical), mouse Mcat (73% identical), rat Mcat (68% identical), rabbit MCAT (67% identical), tropical clawed frog mcat (60% identical), zebrafish mcat (54% identical), Drosophila melanogaster beg (42% identical), Caenorhabditis elegans mcat-1 (36% identical).
Diseases named in the same sentence as MCAT in open-access papers:
MCAT is named in the same sentence as 52 diseases in open-access papers, as found by Europe PMC text mining. Sharing a sentence is not in itself a finding about the gene and the disease. The quoted sentences say what the papers report.
cardiomyopathy (2 papers, 2020). A disease of the heart muscle or myocardium proper. "While normalizing mitochondrial ROS by modest level of mCAT expression attenuates cardiac defects in a model of mitofusin-deficient cardiomyopathy, super-suppression of mitochondrial ROS by high level of mCAT expression exacerbates the defects." (PMID 32648542, 2020). "In order to more decisively determine if elevated ROS contributed to mtCaMKII cardiomyopathy, we took an orthogonal approach, and interbred mtCaMKII mice with mice transgenically overexpressing a mitochondrial-targeted form of catalase (mCat), an enzyme that decomposes H2O2 into H2O and O2." (PMID 32887881, 2020).
diabetes (2 papers, 2017 to 2019). "SREBP is involved in the regulation of various lipogenic genes such as ACACA, FASN, ACSL1 and MCAT which are found to be overexpressed in diabetes." (PMID 31569751, 2019). "Inhibition of MCAT by pharmacological treatment in clinic may be a novel way to cure diabetes." (PMID 29088862, 2017).
gastric cancer (2 papers, 2013 to 2023). A primary or metastatic malignant neoplasm involving the stomach. "This compound is an antibacterial agent targeting malonyl-CoA:acyl carrier protein transacylase (MCAT) from Helicobacter pylori, which can cause chronic gastric inflammation and gastric cancer." (PMID 38140421, 2023).
heart failure (2 papers, 2017 to 2020). Inability of the heart to pump blood at an adequate rate to meet tissue metabolic requirements. "As with mCAT expression, SS-31 ameliorates cardiac fibrosis and improves cardiac function in pressure overload-induced heart failure, and proteomic analyses revealed that both SS-31 and mCAT expression attenuated changes in proteins related to mitochondrial function." (PMID 32648542, 2020). "Results from this study coincides with the current literature which demonstrates the cardioprotective benefit of MCAT upregulation in animal models heart failure and suggests the possibility of designing effective therapeutic strategies to modulate cardiac oxidative stress in sepsis." (PMID 28405943, 2017).
Sepsis (2 papers, 2016 to 2017). Sepsis is defined as life-threatening organ dysfunction caused by a dysregulated host response to infection. "Although augmentation of mitochondrial-oriented free radical scavengers such as MCAT and SOD-2 have shown promising results in animal models of ischemic cardiomyopathy as well as hypertensive heart failure, they have not been adequately explored in the context of sepsis." (PMID 28405943, 2017).
anemia (1 paper, 2021). A reduction in the number of red blood cells, the amount of hemoglobin, and/or the volume of packed red blood cells. "Overexpression of mCAT significantly reduced the elevated serum BUN and attenuated the severe anemia, although many of the mCAT-treated mice still had serum BUN > 100 mg/dL, suggesting the progression of renal failure was delayed but not prevented." (PMID 34671066, 2021).
Insulin resistance (1 paper, 2017). Increased resistance towards insulin, that is, diminished effectiveness of insulin in reducing blood glucose levels. "Besides PTPN1 and STAT5A, some other genes like FASN, TAP1, which are also involved in insulin resistance, have close relationship with MCAT." (PMID 29088862, 2017). "Since PTPN1 and STAT5A were demonstrated to impair insulin signaling, MCAT and its network may be novel mechanisms as to the offspring insulin resistance affected by intrauterine hyperglycemia." (PMID 29088862, 2017). "It is estimated that increased MCAT expression will lead to enhanced fatty acid synthesis and lipotoxicity, which may induce insulin resistance." (PMID 29088862, 2017). "We hypothesized that MCAT expression in the umbilical cord blood from GDM patients would be increased, and the dramatically changed proteins in the network of MCAT may contribute to insulin resistance in the offspring." (PMID 29088862, 2017). "In mitochondria, malonyl-CoA-acyl carrier protein transacylase (MCAT) is the key enzyme of mitochondrial fatty acid synthesis and is estimated to contribute to insulin resistance." (PMID 29088862, 2017). "In this study, we aimed to examine the role of MCAT and its network in the umbilical cord blood in GDM-induced offspring insulin resistance." (PMID 29088862, 2017). "However, specific roles of MCAT in insulin resistance are still unknown and need to be determined." (PMID 29088862, 2017). "The specific role of MCAT in insulin resistance has not been determined." (PMID 29088862, 2017).
optic atrophy 15 (1 paper, 2024). "Mutations in lipid metabolism-related genes, including malonyl CoA:ACP acyltransferase (MCAT) and mitochondrial trans-2-enoyl-CoA reductase (MECR), are responsible for autosomal recessive optic atrophy 16 (OPA15) and optic atrophy 15 (OPA16), respectively." (PMID 39201313, 2024).
cancer (11 papers, 2011 to 2022). A tumor composed of atypical neoplastic, often pleomorphic cells that invade other tissues. "Besides the altered expression of mCAT and cCAT in cancer, increased expression of MPST, the gene encoding for MST, was found in several types of cancer, including liver, colorectal, endometrial, stomach, prostate, urothelial, and pancreatic carcinomas." (PMID 32882966, 2020). "Furthermore, inhibition of cancer cell anchorage-independent growth was also reversed by mCat overexpression." (PMID 24553354, 2014).
tumor (10 papers, 2018 to 2025). "The deficiency of mCAT mice in mROS also did not affected their capacity to control tumor growth, as demonstrated in mice grafted by either B16-OVA or TC-1 tumor cells, confirming that these mice have a functional immune system." (PMID 29884826, 2018).
infection (8 papers, 2008 to 2023). The state of being infected such as from the introduction of a foreign agent such as serum, vaccine, antigenic substance or organism. "In contrast to wild-type BMDMs, IL-1β secretion was significantly up regulated in Nox2-/-, Nos2-/-, and mCAT+/+ BMDMs during ΔpknF mutant infection." (PMID 34324582, 2021). "HA-tagged mCAT-1 and dCAT-1 clones were transfected into three cell lines that are not naturally susceptible to infection by ecotropic mouse gammaretroviruses: MA139 (ferret), Tb-1-Lu (bat lung), and MDCK (canine kidney) cells." (PMID 18186934, 2008).
MCAT also shares sentences with these, for which no sentence is quoted: breast carcinoma (4 papers); hepatocellular carcinoma (4); astrocytoma (2); lung carcinoma (2); MELAS (2); Obesity (2); Parkinson disease (2); autoimmune disease (1); emphysema (1); Encephalopathy (1); endometrial adenocarcinomas (1); endometrial cancer (1); fibrosis (1); focal segmental glomerulosclerosis (1); glioblastoma (1); Glucose intolerance (1); Hypercholesterolemia (1); Hyperglycemia (1); influenza infection (1); ischemia (1); ischemic cardiomyopathy (1); lactic acidosis (1); Leigh syndrome (1); macrosomia (1); MERRF syndrome (1); metabolic disorders (1); Mitochondrial myopathy (1); myocardial infarction (1); myocardial ischemia (1); nasopharyngeal carcinoma (1).
A further 11 diseases each share a sentence with MCAT in 1 paper.